ZFP92 (ZFP92 zinc finger protein)
Description:
KRAB domain-containing zinc-finger protein that represses B1/Alu SINE transposable elements and modulates the transcription of nearby genes in a tissue-specific manner. It regulates glucose homeostasis and lipid metabolism by modulating the expression of the endocrine cell-defining transcription factor, MAFB, in pancreatic islets and, the fat metabolism regulator, ACACB, in adipose tissue and muscle.
Synonyms: ZNF897
Tractability: No criterion of Open Targets' tractability assessment is met for any kind of drug.
Gene: Protein-coding gene on chromosome X (153,411,434 to 153,426,481, forward strand). Ensembl gene ENSG00000189420.
Subcellular location: Nucleus
Gene Ontology:
Molecular function: DNA-binding transcription factor activity, RNA polymerase II-specific; DNA-binding transcription repressor activity, RNA polymerase II-specific; RNA polymerase II cis-regulatory region sequence-specific DNA binding
Biological process: negative regulation of transcription by RNA polymerase II; regulation of glucose metabolic process; regulation of lipid metabolic process; regulation of transcription by RNA polymerase II; transposable element silencing; regulation of DNA-templated transcription
Cellular component: nucleus
Homologues: Orthologues: chimpanzee ZFP92 (99% identical), macaque ZFP92 (97% identical), pig ZFP92 (75% identical), rabbit ZFP92 (73% identical), rat Zfp92 (65% identical), mouse Zfp92 (62% identical), guinea pig ZFP92 (57% identical), zebrafish si:dkey-89b17.4 (24% identical), zebrafish znf646 (24% identical), Drosophila melanogaster CG1602 (18% identical), Drosophila melanogaster az2 (18% identical), Drosophila melanogaster CG18011 (18% identical), and 12 more. Paralogues in human: ZNF420 (34% identical), ZNF48 (34% identical), ZNF91 (34% identical), ZNF84 (33% identical), ZNF160 (32% identical), ZNF497 (32% identical), ZNF107 (32% identical), ZNF689 (32% identical), ZNF845 (31% identical), ZNF99 (31% identical), ZNF184 (31% identical), ZNF569 (31% identical), and 24 more.
Diseases named in the same sentence as ZFP92 in open-access papers:
ZFP92 is named in the same sentence as 2 diseases in open-access papers, as found by Europe PMC text mining. Sharing a sentence is not in itself a finding about the gene and the disease.
ZFP92 shares sentences with these, for which no sentence is quoted: Ovarian Insufficiency (1 paper); schizophrenia (1).